RNU4-30P (RNA, U4 small nuclear 30, pseudogene)
Gene: Small nuclear RNA gene on chromosome 16 (68,329,387 to 68,329,529, reverse strand). Ensembl gene ENSG00000222177.
Homologues: Orthologues: chimpanzee U4 (99% identical), macaque U4 (83% identical), tropical clawed frog U4 (54% identical), rat LOC120097640 (53% identical), tropical clawed frog U4 (51% identical), tropical clawed frog U4 (50% identical), rat LOC120095803 (50% identical), rabbit U4 (49% identical), mouse Gm26425 (44% identical), guinea pig U4 (39% identical), mouse Gm22956 (39% identical), mouse Gm55605 (39% identical). Paralogues in human: RNU4-13P (57% identical), RNU4-28P (56% identical), RNU4-67P (56% identical), RNU4-84P (56% identical), RNU4-76P (55% identical), RNU4-86P (55% identical), RNU4-44P (55% identical), RNU4-53P (55% identical), RNU4-48P (54% identical), RNU4-64P (54% identical), RNU4-12P (53% identical), RNU4-16P (53% identical), and 82 more.